JAKMIP3 (Janus kinase and microtubule interacting protein 3)
Synonyms: C10orf14; C10orf39; JAMIP3; NECC2; FLJ37857; KIAA4091; bA140A10.5
Tractability: PROTAC: ubiquitination databases record sites on it; its protein half-life has been measured.
Gene: Protein-coding gene on chromosome 10 (132,036,336 to 132,184,858, forward strand). Ensembl gene ENSG00000188385.
Subcellular location: Golgi apparatus
Gene Ontology:
Molecular function: kinase binding; microtubule binding
Cellular component: Golgi apparatus
Genetic constraint (gnomAD): Loss-of-function variants: 50 observed, 92.29 expected, observed/expected ratio (o/e) 0.54, 90% interval 0.43 to 0.69. The upper end of that interval is the gene's LOEUF score, 0.69, which puts it in group 2 of 6, group 1 being the genes least tolerant of losing a copy. Missense variants: 908 observed, 1,007.6 expected, observed/expected ratio (o/e) 0.9, 90% interval 0.85 to 0.95. Synonymous variants: 468 observed, 424.01 expected, observed/expected ratio (o/e) 1.1, 90% interval 1.02 to 1.19.
Homologues: Orthologues: chimpanzee JAKMIP3 (96% identical), macaque JAKMIP3 (95% identical), rat Jakmip3 (95% identical), guinea pig JAKMIP3 (94% identical), mouse Jakmip3 (94% identical), pig JAKMIP3 (92% identical), tropical clawed frog jakmip3 (84% identical), dog JAKMIP3 (82% identical), rabbit JAKMIP3 (70% identical), zebrafish jakmip3 (57% identical). Paralogues in human: JAKMIP1 (62% identical), JAKMIP2 (61% identical).
Diseases named in the same sentence as JAKMIP3 in open-access papers:
JAKMIP3 is named in the same sentence as 5 diseases in open-access papers, as found by Europe PMC text mining. Sharing a sentence is not in itself a finding about the gene and the disease. The quoted sentences say what the papers report.
mastitis (1 paper, 2024). Inflammation of breast tissue during lactation or postpartum due to an obstructed duct or infection. "The same region partially overlaps the CNVR_1549_P (the region comprising the JAKMIP3, DPYSL4, STK32C, LRRC27, PWWP2B) resulted associated with clinical mastitis in Mexican Holstein Cattle." (PMID 38771855, 2024).
tumor (2 papers, 2021). "Among genes that have been associated with host variation responsible for tumour regression on devils, we found only JAKMIP3, a Janus kinase and microtubule binding protein, in our list of contemporary candidates." (PMID 34034517, 2021). "However, only mutations of PPIL2 and JAKMIP3 were identified in the progressive tumor and CTCs." (PMID 34616428, 2021).
cardiac disease (1 paper, 2018). "The remaining differentially expressed genes in MuRF1 Tg + hearts after CH exposure associated with alternative splicing (Ptpru, Svopl, Syt16, Ccp110, Jakmip3, Kansl1l) have not been functionally defined in heart and/or cardiac disease to our knowledge." (PMID 30241514, 2018).
JAKMIP3 also shares sentences with these, for which no sentence is quoted: Insulin resistance (1 paper); Obesity (1).